XPR1 (xenotropic and polytropic retrovirus receptor 1)
Description:
Inorganic ion transporter that mediates phosphate ion export across the plasma membrane. Plays a major role in phosphate homeostasis, preventing intracellular phosphate accumulation and possible calcium phosphate precipitation, ultimately preserving calcium signaling. Binds inositol hexakisphosphate (Ins6P) and similar inositol polyphosphates, such as 5-diphospho-inositol pentakisphosphate (5-InsP7), which are important intracellular signaling molecules involved in regulation of phosphate flux.
Synonyms: SLC53A1; SYG1; X3; IBGC6
Tractability: Small molecule: a structure with a bound ligand is known. Antibody: UniProt places it where antibodies can reach, with high confidence; its Gene Ontology location is reachable by antibodies, with high confidence; UniProt predicts a signal peptide or a membrane-spanning region. PROTAC: ubiquitination databases record sites on it; its protein half-life has been measured.
Gene: Protein-coding gene on chromosome 1 (180,632,016 to 180,890,279, forward strand). Ensembl gene ENSG00000143324.
Subcellular location: Cell membrane
Gene Ontology:
Molecular function: efflux transmembrane transporter activity; inositol hexakisphosphate binding; phosphate transmembrane transporter activity; virus receptor activity
Biological process: intracellular phosphate ion homeostasis; phosphate ion transmembrane transport; symbiont entry into host cell
Cellular component: plasma membrane; membrane
Genetic constraint (gnomAD): Loss-of-function variants: 25 observed, 81.12 expected, observed/expected ratio (o/e) 0.31, 90% interval 0.22 to 0.43. The upper end of that interval is the gene's LOEUF score, 0.43, which puts it in group 1 of 6, group 1 being the genes least tolerant of losing a copy. Missense variants: 537 observed, 871.67 expected, observed/expected ratio (o/e) 0.62, 90% interval 0.57 to 0.66. Synonymous variants: 293 observed, 314.91 expected, observed/expected ratio (o/e) 0.93, 90% interval 0.85 to 1.02.
Homologues: Orthologues: chimpanzee XPR1 (100% identical), macaque XPR1 (99% identical), dog XPR1 (98% identical), guinea pig XPR1 (96% identical), mouse Xpr1 (95% identical), rabbit XPR1 (94% identical), rat Xpr1 (94% identical), pig XPR1 (93% identical), tropical clawed frog xpr1 (85% identical), zebrafish xpr1a (80% identical), Caenorhabditis elegans Y39A1A.22 (47% identical).
Diseases named in the same sentence as XPR1 in open-access papers:
XPR1 is named in the same sentence as 49 diseases in open-access papers, as found by Europe PMC text mining. Sharing a sentence is not in itself a finding about the gene and the disease. The quoted sentences say what the papers report.
Fahr's disease (4 papers, 2020 to 2024). "Genes implicated in Fahr's disease include PDGFB, PDGFRB, SLC20A2, XPR1, MYORG, and JAM2." (PMID 37780723, 2023).
Fanconi syndrome (3 papers, 2019 to 2024). "Kidney-specific knockout of XPR1 in mice causes Fanconi syndrome and hypophosphatemic rickets, underpinning an essential role of XPR1 in transcellular Pi transport." (PMID 38507112, 2024). "For example, renal-specific knockout of XPR1 in mice causes hypophosphatemia rickets and Fanconi syndrome." (PMID 31186349, 2019). "Conditional knockout of mouse kidney Xpr1 results in reduced proximal tubule Pi efflux, hypophosphatemia, and other abnormalities similar to Fanconi syndrome, which is consistent with XPR1 being the basolateral exit pathway for Pi in the proximal tubule." (PMID 37063296, 2023).
hyperphosphatemia (3 papers, 2022 to 2023). Abnormally high level of phosphate in the blood. "A syndrome of high [Pi] in serum, hyperphosphatemia, is a risk factor in chronic kidney disease, afflicting over six hundred million people globally, and Xpr1 could be a possible therapeutic target for hyperphosphatemia." (PMID 37949217, 2023). "In Nx6 animals that exhibited hyperphosphatemia, we found Slc20a1/2, Xpr1, and Mapk1/3 to be downregulated, suggesting opposite effects of longer bone exposure on increased extracellular Pi in the regulation of gene expression in in vitro vs. short-term in vitro studies." (PMID 37108433, 2023). "The second pathway is the impairment of brain Pi homeostasis, either by hyperphosphatemia or by disrupted transport of phosphate in the brain; these patients suffering from this pathway defects may have mutations in SLC20A2, XPR1, or GNAS gene and usually show significantly increased CSF Pi levels." (PMID 36443312, 2022).
ovarian carcinoma (3 papers, 2019 to 2025). A malignant neoplasm originating from the surface ovarian epithelium. "Knocking out XPR1 caused phosphate accumulation in cells, which, in turn, led to ovarian cancer cell death." (PMID 40641524, 2025). "Using the CRISPR-Cas9 loss-of-function strategy, XPR1 was found to promote ovarian cancer growth." (PMID 40641524, 2025). "Moreover, XPR1 expression was associated with ovarian cancer's overall survival and progression-free survival." (PMID 40641524, 2025). "We found that the higher the expression of XPR1 in ovarian cancer tissue, the higher the clinical stage of ovarian cancer." (PMID 40641524, 2025). "Simultaneously, it was discovered that XPR1 enhanced the production of MHC-I molecules in ovarian cancer cells." (PMID 40641524, 2025). "Simultaneously, an examination of the TCGA database revealed an elevation in XPR1 protein levels in ovarian cancer in contrast to normal ovarian tissue." (PMID 40641524, 2025). "XPR1 facilitated the growth, invasion, and metastasis of ovarian cancer cells in epithelial ovarian cancer with the CRISPR/Cas9 system." (PMID 40641524, 2025). "Silencing XPR1 combined with the treatment with autophagy inhibitor chloroquine significantly inhibited tumor growth in mouse ovarian cancer models." (PMID 40641524, 2025). "The primary objective of this research was to examine the involvement and impact of XPR1 in ovarian cancer, with a specific emphasis on its function and process in autophagy." (PMID 40641524, 2025). "We examined the effect of silencing or overexpressing XPR1 on SKOV3 and A2780 ovarian cancer cells to clarify the effect of XPR1 on the malignant biology of ovarian cancer." (PMID 40641524, 2025). "We also found that XPR1 expression increased in ovarian cancer, and its high expression indicated ovarian cancer staging and a worse prognosis." (PMID 40641524, 2025). "This study found that XPR1 expression was up-regulated in ovarian cancer tissues, and its high expression was related to the ovarian cancer stage, overall survival, and progression-free survival." (PMID 40641524, 2025). "In conclusion, our research revealed that XPR1 controlled the MHC-I expression in ovarian cancer cells by utilizing the autophagy pathway." (PMID 40641524, 2025). "In ovarian cancer cells, either knocking out XPR1 or inhibiting XPR1 with drugs results in the harmful buildup of phosphate inside the cells, ultimately causing cell death." (PMID 40641524, 2025). "The purpose of this research was to investigate the impact of XPR1 on controlling autophagy in ovarian cancer." (PMID 40641524, 2025). "Silencing XPR1 combined with the autophagy inhibitor chloroquine significantly inhibited tumor growth in mouse ovarian cancer models." (PMID 40641524, 2025). "Inhibiting XPR1 along with chloroquine led to a significant decrease in the growth of ovarian cancer cells in a live organism." (PMID 40641524, 2025). "We used next-generation sequencing to detect the transcriptomic change pattern of ovarian cancer SKOV3 cells after silencing XPR1 to further investigate the mechanism of XPR1 regulation of autophagy." (PMID 40641524, 2025). "In conclusion, the findings indicate that XPR1 could serve as a promising target for the diagnosis and treatment of ovarian cancer." (PMID 40641524, 2025). "The findings indicated that XPR1 could serve as a promising target for diagnosing and treating ovarian cancer." (PMID 40641524, 2025). "Additionally, we discovered that the inhibition of ovarian cancer lesion growth was achieved by combining targeted XPR1 with autophagy inhibitors." (PMID 40641524, 2025). "XPR1 enhanced the growth and spread of ovarian cancer while suppressing autophagy." (PMID 40641524, 2025). "In nude mice, the growth of ovarian cancer SKOV3 cells was enhanced by the overexpression of XPR1." (PMID 40641524, 2025). "XPR1 was either silenced or overexpressed in the ovarian cancer cell lines SKOV3 and A2780." (PMID 40641524, 2025).
ovarian carcinoma (continued). "The findings suggested an increase in XPR1 expression in ovarian cancer tissues." (PMID 40641524, 2025). "This suggested the involvement of XPR1 in ovarian cancer growth and autophagy." (PMID 40641524, 2025). "XPR1 was found to be mainly localized in the cell and membrane in ovarian cancer tissues." (PMID 40641524, 2025). "We used immunohistochemistry to detect the expression pattern of XPR1 in ovarian cancer." (PMID 40641524, 2025). "Finally, the role of XPR1 in the occurrence of ovarian cancer needs to be confirmed using XPR1 gene knockout and transgenic mice." (PMID 40641524, 2025). "In C57 mice, the growth of ovarian cancer ID8 cells was enhanced by the overexpression of XPR1." (PMID 40641524, 2025). "Consequently, we investigated how XPR1 impacts the expression of MHC-I in SKOV3 ovarian cancer cells." (PMID 40641524, 2025). "The higher the stage of XPR1 in ovarian cancer tissue, the higher its expression." (PMID 40641524, 2025). "We first examined the expression of XPR1 to clarify its role in ovarian cancer." (PMID 40641524, 2025). "This implies that XPR1 may serve as a marker for diagnosing and predicting the outcome of ovarian cancer." (PMID 40641524, 2025). "Nevertheless, the function and operation of the XPR1 protein in autophagy and evasion of the immune system by ovarian cancer cells remain unknown." (PMID 40641524, 2025). "Additionally, it was discovered that XPR1 enhanced the proliferation of ovarian carcinoma." (PMID 40641524, 2025). "Lysosome quantity rose following XPR1 inhibition in SKOV3 and A2780 ovarian cancer cells, contrasting with a decline following XPR1 up-regulation." (PMID 40641524, 2025). "Also, silencing XPR1 could induce the apoptosis of ovarian cancer cells." (PMID 40641524, 2025). "Simultaneously, XPR1 and LAMP1 proteins were found to be in the same location in the cytoplasm of SKOV3 and A2780 cells from ovarian cancer." (PMID 40641524, 2025). "XPR1 regulated the localization and expression of MHC-I molecules in the ovarian cancer cell membrane through autophagy." (PMID 40641524, 2025). "XPR1 controlled the positioning and production of MHC-I molecules on the surfaces of ovarian cancer cells via autophagy." (PMID 40641524, 2025). "Therefore, XPR1 could serve as a promising target for treating ovarian cancer." (PMID 40641524, 2025). "Therefore, XPR1 could be a potential therapeutic target for ovarian cancer." (PMID 40641524, 2025). "For RFS of patients with ovarian cancer, SPOCK2 and FAXDC2 were unfavorable prognostic biomarkers but ADAMDEC1, CCNA2, FAM181A, FOXA2, LRRTM1, NEIL3 and XPR1 were favorable prognostic biomarkers." (PMID 31794425, 2019). "High expression of GJB2, S100A2, SPOCK2, TGM1or EPS8 indicated a poor OS of patients with ovarian cancer, whereas ovarian cancer patients with higher expression of ADAMDEC1, CHEK1, EGFL6, FAM181A, FOXA2, LYPD1, PART1 or XPR1 possessed better OS." (PMID 31794425, 2019). "Silencing XPR1 in SKOV3 and A2780 ovarian cancer cells resulted in a notable rise in red dots." (PMID 40641524, 2025). "Additionally, it was discovered that the levels of LAMP1 protein rose following XPR1 suppression, but decreased with XPR1 up-regulation in SKOV3 and A2780 ovarian cancer cells." (PMID 40641524, 2025).
tongue squamous cell carcinoma (3 papers, 2019 to 2023). A squamous cell carcinoma that arises from the tongue. "Real-time PCR and western blotting assay were used to measure the expression of XPR1 in tongue squamous cell carcinoma (TSCC) tissues." (PMID 30995931, 2019). "For example, XPR1 could promote progression of tongue squamous cell carcinoma via activation of NF-κB signaling." (PMID 37407973, 2023). "In addition, the XPR1-induced NF-κB pathway was related to many aspects of tongue squamous cell carcinoma, including the tumor grade and patient prognosis." (PMID 34550272, 2021). "Moreover, previous study reported that XPR1 could promote progression of tongue squamous cell carcinoma via NF-κB signaling, which indicated that XPR1 may also act as an oncogene related to cancer." (PMID 37407973, 2023).
calcification (2 papers, 2024). Process by which organic tissue becomes hardened by the physiologic deposit of calcium salts. "Malfunctions in XPR1 are associated with human diseases, such as primary familial brain calcification and certain cancers, highlighting its critical role in maintaining Pi homeostasis." (PMID 39711567, 2024).
esophageal squamous cell carcinoma (2 papers, 2022 to 2023). Esophageal squamous cell carcinoma (ESCC) is a type of esophageal carcinoma (EC) that can affect any part of the esophagus, but is usually located in the upper or middle third. "XPR1 could also promote the tumorigenicity of esophageal squamous cell carcinoma." (PMID 37407973, 2023).
leukemia (2 papers, 2015 to 2019). A malignant (clonal) hematologic disorder, involving hematopoietic stem cells and characterized by the presence of primitive or atypical myeloid or lymphoid cells in the bone marrow and the blood. "Xenotropic and polytropic retrovirus receptor 1 (XPR1), a previously identified cellular receptor for several murine leukemia viruses, plays a role in many pathophysiological processes." (PMID 30995931, 2019). "We focus here on the receptor gene Xpr1 (xenotropic and polytropic retrovirus receptor 1) for murine leukemia viruses (MLVs)." (PMID 26555287, 2015).
osteoporosis (2 papers, 2020 to 2021). A condition of reduced bone mass, with decreased cortical thickness and a decrease in the number and size of the trabeculae of cancellous bone (but normal chemical composition), resulting in increased fracture incidence. "XPR1, SLC4A2, and GNPTAB were previously reported to be related to osteoporosis, but GRAMD1B, ITGA6, and DUSP6 have never been studied with respect to any musculoskeletal-related diseases." (PMID 34475393, 2021).
ovarian clear cell cancer (2 papers, 2023 to 2025). An invasive malignant neoplasm that arises from the ovary and is characterized by a predominance of clear and hobnail malignant epithelial cells. "XPR1 was pinpointed as a gene linked to the progression of ovarian clear cell carcinoma through the utilization of the CRISPR/Cas9 system." (PMID 40641524, 2025).
asthma (1 paper, 2021). "However, the second variant, XPR1, has already been mentioned to play a role in modulating human airway smooth muscle (ASM) contraction, cell growth, and proinflammatory cytokine production that promote bronchoconstriction, airway inflammation, and remodeling in asthma." (PMID 33628342, 2021).
atherosclerosis (1 paper, 2020). A disease characterized by the build-up of fatty material and calcium deposition in the arterial wall resulting in partial or complete occlusion of the arterial lumen. "Xpr1 and Taf3, a regulator of macrophage differentiation and a core transcription factor, which were detected in mouse PVAT, were significantly upregulated during atherosclerosis, suggesting a role in the pathogenesis of atherosclerosis." (PMID 33391033, 2020).
cognitive decline (1 paper, 2019). "Recently, mutations in four different genes (SLC20A2, PDGFRB, PDGFB, and XPR1) were identified, together with novel mutations in the Myogenic Regulating Glycosylase gene, causing the occurrence of movement disorders, cognitive decline, and psychiatric symptoms." (PMID 31267306, 2019).
dementia (1 paper, 2025). Loss of intellectual abilities interfering with an individual's social and occupational functions. "Notably, other related genes, such as “PDGFRB,” “MYORG,” “XPR1,” and “JAM2,” as well as phenotypic traits like “dementia” and “parkinsonism,” also exhibited significant node sizes." (PMID 40456615, 2025).
glioma (1 paper, 2023). A benign or malignant brain and spinal cord tumor that arises from glial cells (astrocytes, oligodendrocytes, ependymal cells). "In order to figure out the oncogene associated with glioma, we selected five genes to preform qRT-PCR experiments, including XPR1, QKI, CREB5, ACVR2B and ABL2." (PMID 37407973, 2023). "Taking the intersection between them, we presumed that XPR1 was the candidate targeted gene between miR-515-5p and miR-582-3p in glioma." (PMID 37407973, 2023). "Collectively, our results confirmed that IGF2BP3/circGNB1/miR-515-5p/miR-582-3p/XPR1 axis could promote tumorigenesis and malignant progression of glioma via IL6/JAK2/STAT3 signaling pathway." (PMID 37407973, 2023). "In addition, previous studies revealed that XPR1, ACVR2B and CREB5 could promote progression of diverse cancers, but they were not reported in glioma." (PMID 37407973, 2023).
head and neck cancer (1 paper, 2019). A primary or metastatic malignant neoplasm affecting the head and neck. "Interestingly, analysis with the Cancer Genome Atlas (TCGA) Head and Neck Cancer (HNSCC) dataset suggested that XPR1 was robustly increased in tumor samples compared to normal tissues." (PMID 30995931, 2019). "We then validated the upregulation of XPR1 in TSCC, a common subtype of head and neck cancer." (PMID 30995931, 2019).
lentivirus infection (1 paper, 2019). Virus diseases caused by the Lentivirus genus. "To investigate the biological role of XPR1, we first stably expressed XPR1 in TSCC cell lines SCC25 and CAL-27 by lentivirus infection." (PMID 30995931, 2019).
lung adenocarcinoma (1 paper, 2025). A carcinoma that arises from the lung and is characterized by the presence of malignant glandular epithelial cells. "RBM15 stabilized XPR1 mRNA through m6A modification to regulate lung adenocarcinoma cell proliferation, invasion, apoptosis, oxidative stress and ferroptosis." (PMID 40682199, 2025).
neuroblastoma (1 paper, 2012). Neuroblastoma (NB) is the most common solid, extracranial childhood tumor. "A study of XMRV-induced apoptosis of SY5Y human neuroblastoma cells identified its receptor, Xpr1, as a novel atypical G-protein-coupled receptor (GPCR)." (PMID 23028701, 2012).
prostate carcinoma (1 paper, 2011). A carcinoma that arises from epithelial cells of the prostate gland. "However, prostate cancer cells of epithelial origin express XPR1 and are susceptible to XMRV infection." (PMID 22312343, 2011). "XPR1 RNA was shown to be present in human prostate stromal fibroblasts but absent in prostatic epithelial and smooth muscle cell lines, consistent with some previous findings that XMRV viral antigens are present in prostatic stromal fibroblasts of prostate cancer patients." (PMID 22312343, 2011).